PTPN21 (protein tyrosine phosphatase non-receptor type 21)
Synonyms: PTPD1; PTPRL10
Tractability: No criterion of Open Targets' tractability assessment is met for any kind of drug.
Target class: Tyrosine protein phosphatase; Enzyme; Phosphatase; Protein Phosphatase
Gene: Protein-coding gene on chromosome 14 (88,465,778 to 88,555,013, reverse strand). Ensembl gene ENSG00000070778.
Subcellular location: Cytoplasm, cytoskeleton
Subcellular location (Human Protein Atlas): Cytosol; Golgi apparatus
Gene Ontology:
Molecular function: protein binding; protein tyrosine phosphatase activity
Biological process: positive regulation of hippo signaling; protein dephosphorylation
Cellular component: cytoskeleton
Genetic constraint (gnomAD): Loss-of-function variants: 60 observed, 102.12 expected, observed/expected ratio (o/e) 0.59, 90% interval 0.48 to 0.73. The synonymous counts are far from expectation, so gnomAD's model fits this gene poorly and the ratio says little. Missense variants: 1,407 observed, 1,337 expected, observed/expected ratio (o/e) 1.05, 90% interval 1.01 to 1.1. Synonymous variants: 658 observed, 558.13 expected, observed/expected ratio (o/e) 1.18, 90% interval 1.11 to 1.26.
Homologues: Orthologues: chimpanzee PTPN21 (99% identical), macaque PTPN21 (98% identical), rabbit PTPN21 (92% identical), dog PTPN21 (90% identical), mouse Ptpn21 (89% identical), pig PTPN21 (89% identical), rat Ptpn21 (89% identical), guinea pig PTPN21 (87% identical), tropical clawed frog ptpn21 (79% identical), zebrafish ptpn21 (73% identical). Paralogues in human: PTPN14 (55% identical), PTPRF (19% identical), PTPRS (18% identical), PTPRD (18% identical), PTPRB (17% identical), PTPRZ1 (16% identical), PTPRM (16% identical), PTPRT (16% identical), PTPRK (15% identical), PTPN23 (15% identical), PTPN3 (15% identical), PTPRG (15% identical), and 23 more.
Diseases named in the same sentence as PTPN21 in open-access papers:
PTPN21 is named in the same sentence as 23 diseases in open-access papers, as found by Europe PMC text mining. Sharing a sentence is not in itself a finding about the gene and the disease. The quoted sentences say what the papers report.
bladder cancer (4 papers, 2016 to 2024). "Moreover, PTPN21 is highly expressed in tumor samples from bladder carcinoma, and a catalytically inactive mutation of PTPN21 was shown to inhibit the growth and migration of bladder cancer cells." (PMID 38416831, 2024). "Additionally, mutations in PTPN21 have been reported in both bladder cancer and colorectal tumors." (PMID 26527318, 2016). "Given its inverse correlation with tumor invasion in bladder cancer tissues and its immunosuppressive function, PTPN21 may influence the early stages of tumor progression by inhibiting the immunosuppressive TIME and tumor invasion." (PMID 34855841, 2021). "Knockout of PTPN21 promotes EGFR degradation and inhibition of downstream ERK signaling, thereby reducing the growth and motility of bladder cancer cells." (PMID 36106167, 2022).
breast carcinoma (3 papers, 2014 to 2022). "Genes co-expressed with PTPN21 were correlated with “Signal transduction_IGF-1 receptor signaling pathway”, “Cytoskeleton remodeling_Regulation of actin cytoskeleton organization by the kinase effectors of Rho GTPases”, and “Breast cancer (general schema)”." (PMID 36556168, 2022). "Our migration assay showed that the expression level of PTPN21 did not affect the migration potential of BM-MSCs themselves, while the potential of PTPN21-overexpressed BM-MSCs recruiting human breast cancer cells and vascular endothelial cells was significantly higher than BM-MSC control cells." (PMID 31885609, 2019).
leukemia (3 papers, 2016 to 2025). A malignant (clonal) hematologic disorder, involving hematopoietic stem cells and characterized by the presence of primitive or atypical myeloid or lymphoid cells in the bone marrow and the blood. "Future investigations should explore the unique role of PTPN21 in stem cell-like cells, particularly through the study of leukemia stem cells." (PMID 40305474, 2025). "This study is the first to confirm that both PTPN21 and USP54 are mutated in human leukemia." (PMID 26527318, 2016). "In addition to gene mutations that are known to be involved in leukemogenesis, such as ones in MYC and KRAS, we also identified mutations within PTPN21, TBX21, USP54, USP11, NCOR2, CSPP1 that have never before been identified in human leukemia." (PMID 26527318, 2016).
acute lymphoblastic leukemia (2 papers, 2019 to 2025). Leukemia with an acute onset, characterized by the presence of lymphoblasts in the bone marrow and the peripheral blood. "In this study, we observed that high PTPN21 expression hindered acute lymphoblastic leukemia (ALL) cell apoptosis induced by the chemotherapeutic drugs vincristine (VCR) and daunorubicin (DNR)." (PMID 40305474, 2025). "To investigate the role of PTPN21 in acute lymphoblastic leukemia (ALL), we overexpressed PTPN21 in Jurkat and NALM-6 cells, while cells transfected with the pHIV7-SFFV-GFP vector served as a control." (PMID 40305474, 2025). "In conclusion, our study revealed that the overexpression of PTPN21 in acute lymphoblastic leukemia (ALL) cells markedly impairs the induction of apoptosis by DNR and VCR." (PMID 40305474, 2025). "To confirm the pivotal role of GADD45A in PTPN21-mediated antiapoptotic effects in acute lymphoblastic leukemia (ALL) cells, we restored the expression of GADD45A through lentiviral transfection, while cells transfected with the pHIV7-SFFV-GFP vector served as a control." (PMID 40305474, 2025). "Secondly, our findings indicate that the expression of PTPN21 may impact the therapeutic efficacy of vincristine (VCR) in acute lymphoblastic leukemia (ALL) cells, potentially contributing to the development of drug resistance." (PMID 40305474, 2025). "Nevertheless, it remains unclear whether PTPN21 impacts the effects of VCR and DNR on acute lymphoblastic leukemia." (PMID 40305474, 2025). "Our previous research demonstrated that non-receptor-typed PTP21 (PTPN21), a member of the PTP family, played a critical role in the proliferation, cell cycle, and chemosensitivity of acute lymphoblastic leukemia cells." (PMID 31885609, 2019).
colorectal cancer (2 papers, 2008 to 2020). A primary or metastatic malignant neoplasm that affects the colon or rectum. "In a similar approach, differential expression of the human PTPN21 gene was observed when comparing MSI-H with microsatellite stable (MSS) colorectal cancer cell lines and mutations in this gene were reported to occur in a subset of MSI-H colorectal carcinomas." (PMID 19000305, 2008). "Different from these results, PTPN22 was downregulated in stomach cancer cell lines and PTPN21 were increased in colorectal cancer cell lines, which were inconsistent with the conclusions of Oncomine and Ualcan database." (PMID 32536826, 2020). "The expression profiles of PTPN21 in colorectal cancer and PTPN22 in stomach cancer warrant further examination." (PMID 32536826, 2020). "Our results provide evidence for frameshift mutations in six of these PTP genes (PTPN21, PTPRS, PTPN5, PTPN23, PTPRA, PTPRE) affecting about 32% of MSI-H colorectal cancers." (PMID 19000305, 2008). "For colorectal cancer (CRC), PTPN2, PTPN21 and PTPN22 levels were correlated with incidence; expression of PTPN5, PTPN12, and PTPN14 was correlated with TNM stage and N stage; high PTPN5 or PTPN7 expression was associated with increased hazards of death." (PMID 32536826, 2020).
colorectal tumors (2 papers, 2008 to 2016). "Two genes, PTPN21 and PTPRS, were most frequently affected in primary colorectal tumors (16% and 12%, respectively)." (PMID 19000305, 2008).
schizophrenia (2 papers, 2019 to 2020). A major psychotic disorder characterized by abnormalities in the perception or expression of reality. "PTPN21 (protein tyrosine phosphatase, non-receptor type 21), a protein-coding gene which can positively influence cortical neuronal survival and enhance neuritic length, was identified as a potential risk gene for schizophrenia, showing a reduction in nucleotide diversity in FZ buffalo." (PMID 32993537, 2020).
adenoma (1 paper, 2008). A neoplasm arising from the epithelium. "Furthermore, the observation of 2 mutations within a set of 17 MSI-H adenomas in PTPN21 argues for an early event in malignant transformation." (PMID 19000305, 2008).
colon cancer (1 paper, 2008). "By analogy, we hypothesize that inactivation of PTPN21 by cMNR frameshift mutations in MSI-H colon cancer cells might lead to Etk inactivation and subsequent inhibition of apoptosis." (PMID 19000305, 2008).
colorectal adenoma (1 paper, 2008). An adenoma that arises from the colon or rectum. "From our analysis of preneoplastic lesions we further conclude that PTPN21 frameshift mutations also occur in MSI-H colorectal adenomas albeit at lower frequency (12%) thereby indicating an early step during MSI tumorigenesis." (PMID 19000305, 2008). "Since mutations in the A8 coding repeat of PTPN21 were the most frequent genetic alterations shared by MSI-H cancer cell lines and primary tumors we also analyzed this coding repeat in 17 MSI-H and 6 MSS colorectal adenoma samples." (PMID 19000305, 2008).
glioma (1 paper, 2022). A benign or malignant brain and spinal cord tumor that arises from glial cells (astrocytes, oligodendrocytes, ependymal cells). "PTPN21 was upregulated in glioma tissues, and a high PTPN21 level predicted poor survival rates in glioma patients." (PMID 36556168, 2022).
retinal diseases (1 paper, 2025). "The Ptpn21-/- KO mouse excluded association of Ptpn21 with the retinal disease." (PMID 41325489, 2025). "As the [SPATA7/PTPN21]DEL variant deleted coding regions of two genes, one linked to retinal disease, we considered it a very likely putative causative variant." (PMID 41325489, 2025). "While the role of SPATA7 for retinal disease has been established in human patients and genetically engineered mice, the role of PTPN21 in the retina is unclear even though it is expressed in rod and cone photoreceptors." (PMID 41325489, 2025). "To investigate a potential contributory role of PTPN21 on the retinal disease phenotype, we analyzed Ptpn21-/- knockout (KO) mice that were previously generated by deleting exons 3–10 through a conventional gene targeting approach, resulting in a Ptpn21 null allele." (PMID 41325489, 2025).
tumor (11 papers, 2008 to 2026). "In the five-gene signatures in the ceRNA network, the expression levels of DEPDC1, CPS1, COL9A3, and PTPN21 were significantly different between early- and advanced-stage tumor tissues." (PMID 34855841, 2021). "BM-MSCs overexpressing PTPN21 had an impaired immunosuppressive function and an increased capacity of recruiting tumor cells and vascular endothelial cells in a chemotaxis transwell coculture system." (PMID 31885609, 2019). "We also found a significant mutational enrichment within the tumor-associated transmembrane signal transduction genes KRAS, PTPN21, and USP54 of relapsed patients." (PMID 26527318, 2016). "Additionally, PTPN21-upregulated BM-MSCs showed impaired immunosuppressive potential and accelerate recruitment of tumor cells and vascular endothelial cells." (PMID 31885609, 2019). "Furthermore, the variant frequencies in the tumor of five mutations within the OXTR, TBX21, CSPP1, and PTPN21 genes ranged from 40%–50% in the primary tumor, thus suggesting the likelihood that these were present in virtually all tumor cells at the onset (heterozygosity)." (PMID 26527318, 2016). "Notably, the correlation between PTPN21 and multiple immune cell markers, such as CD4 + T cells and macrophages, hints at its potential role in regulating the tumor immune microenvironment, paving the way for the development of novel therapeutic strategies." (PMID 40305474, 2025). "We analyzed the expression levels of PTPNs in the TCGA database and discovered that PTPN1, PTPN6, PTPN7, PTPN18, PTPN20, and PTPN22 were significantly upregulated in tumor samples, while PTPN4, PTPN5, PTPN10, PTPN11, PTPN13, PTPN14, and PTPN21 were downregulated in tumor samples." (PMID 36226189, 2022). "For instance, inhibiting PTPN21 to curb the proliferation of ALL cells, in conjunction with TKIs or other immunotherapies, could further bolster the eradication capabilities against tumor cells." (PMID 40305474, 2025).
cancer (8 papers, 2008 to 2025). A tumor composed of atypical neoplastic, often pleomorphic cells that invade other tissues. "PTPN21 is known to be up-regulated in several types of cancer cells, and its mutations are found in many patients with cancer." (PMID 38416831, 2024). "PTPN21 has been previously linked to the development of various cancers." (PMID 40305474, 2025). "In addition, mutations in PTPN21 have also been identified in several human cancers such as colorectal tumors, colon cancer, endometrial cancers, and acute lymphoblastic leukemia." (PMID 38416831, 2024). "Although the expression of PTPN21 has been correlated with immune infiltration levels in various cancers, the specific mechanisms of its action in ALL remain to be thoroughly explored." (PMID 40305474, 2025). "Recent reports have highlighted the altered expression of PTPN21 in the development of various cancers, such as bladder cancer, gastric cancer, pancreatic carcinoma, and glioma." (PMID 40305474, 2025). "Among these mRNAs, the prognostic values and mechanisms of LMF1, PPM1L, and PTPN21 have rarely been reported in cancers." (PMID 36829221, 2023). "Moreover, PTPNs expressions except for PTPN5, PTPN13, and PTPN21 were significantly upregulated in the tumorous compared with those in normal tissues in 20 cancers in the TCGA pan-cancer." (PMID 37884566, 2023). "Further studies suggested that PTPN7 significantly activated apoptosis, and EMT pathway in pan-cancer, PTPN2 significantly activated apoptosis and cell cycle pathway in pan-cancer, while PTPN21 significantly inhibited apoptosis and cell cycle pathway in pan-cancer." (PMID 37884566, 2023). "However, phosphoproteomics of both cancer and embryonic stem cells revealed that PTPN21 contains multiple tyrosine phosphorylated residues." (PMID 24847354, 2014). "A total of 20 target mRNAs of three miRNAs were predicted, among which seven target mRNAs—ASAP3, BCL2L2, LMF1, PPM1L, PTPN21, SLC18A2, and NR3C2—had prognostic value; PRKACB, PDCD4, RPS6KA5, and BCL2L2 were enriched in the miRNA cancer pathway." (PMID 36829221, 2023).
cardiovascular disease (1 paper, 2022). "In summary, the hub genes related with M2 macrophages that we searched include CCL22, C1orf105, GAP43, and PTPN21, all of which imply a relationship with cardiovascular disease, which is consistent with our findings." (PMID 36222281, 2022).
infection (1 paper, 2019). The state of being infected such as from the introduction of a foreign agent such as serum, vaccine, antigenic substance or organism. "Because a previous report indicated that PTPN21 is another regulator of the Hippo pathway signaling that interferes with YAP activity, as does PTPN14, it might be reasonable to hypothesize that HPV targets PTPN21 via its E7 protein during infection." (PMID 31323018, 2019).
PTPN21 also shares sentences with these, for which no sentence is quoted: atherosclerosis (1 paper); cone-rod dystrophy (1); lung carcinoma (1); Parkinson disease (1); prostate carcinoma (1); retinal degeneration (1); stomach cancer (1).